CD36 (CD36 molecule (CD36 blood group))
Diseases named in the same sentence as CD36 in open-access papers (continued):
Sharing a sentence is not in itself a finding about the gene and the disease.
tumor (continued). "Despite its well‐established function, the roles of CD36 in different tumors are contradictory, underscoring the complexity of its involvement in tumor biology." (PMID 41267927, 2025). "Cluster of differentiation 36 (CD36), a fatty acid transporter, plays controversial roles in tumor progression." (PMID 41267927, 2025). "CD36 is an important membrane channel protein for the cellular uptake of FAs and plays important roles in tumor metabolism, immunity, drug resistance, progression and metastasis, and CD36 is highly expressed in Enz‐resistant PCa cells." (PMID 39736148, 2025). "Tumor-infiltrating CD8+ T cells mediate the uptake of oxidized lipids (such as oxysterols) through CD36, leading to increased intracellular lipid peroxide accumulation and inducing autophagic ferroptosis, which significantly reduces their antitumor activity." (PMID 40535125, 2025). "Lipid transfer from adipocytes to tumor cells occurs via FATPs, CD36, and FABP4, as previously reported." (PMID 40616161, 2025). "Within CAFs, CD36 regulates lipid uptake and matrix protein production, contributing to tumor proliferation and angiogenesis through vascular mimicry." (PMID 40940956, 2025). "In GI, several specific cell types express CD36, contributing to tumor progression and immune evasion." (PMID 40051496, 2025). "Mechanistically, PLIN2 accelerates CRC progression via a dual mechanism: it induces macrophage reprogramming towards the tumor-promoting M2 phenotype, while simultaneously triggering the CD36-dependent EMT cascade in CRC cells." (PMID 40640171, 2025). "Targeting TAM lipid metabolism through CD36 inhibition combined with agents that impair tumor cell lipid utilization (e.g., FAO inhibitors) generates synthetic lethality." (PMID 40904700, 2025). "A similar critical role of CD36 in cancer growth and chemoresistance has been reported in multiple tumor types, including breast cancer, gastric cancer, and hepatocellular carcinoma." (PMID 40552664, 2025). "CD36 or regulated CAFs, via reprogramming of tumor cell lipid metabolism, shadowed tumor proliferation and migration." (PMID 40698038, 2025). "This offers a direct mechanism by which CD36-mediated lipid metabolism contributes to tumor immune escape." (PMID 41212437, 2025). "The proportion of tumor hybrid cells in co-cultures supplemented with 40 μg/ml and 80 μg/ml CD36 antibody was 1.8% and 1.9%, respectively." (PMID 39752516, 2025). "They selectively process and transfer specific lipids, such as CD36‐released free fatty acids, to fuel β‐oxidation in metastasis‐initiating tumor cells." (PMID 40904700, 2025). "It is also anticipated that the tumor immunosuppressive milieu would be reversed by targeted intervention of important molecules involved in tumor lipid metabolism, such as CD36 and CPT1A." (PMID 41451233, 2025). "Lipid‐laden TAMs transfer fatty acids via CD36 to adjacent tumor cells, fueling β‐oxidation and supporting the survival of metastasis‐initiating cells." (PMID 40904700, 2025). "Targeting the CD36 fatty acid transporter with monoclonal antibodies has been shown to effectively block fatty acid uptake and lipid metabolism in tumor-infiltrating Tregs." (PMID 40051496, 2025). "One possibility is that cooperation between CD36-positive and CD36-negative cells facilitates tumor invasion for secondary tumor metastases." (PMID 40563926, 2025). "CD36, a transmembrane glycoprotein that is expressed in a variety of cell types including tumour cells in malignancies, is involved in lipid homeostasis, angiogenesis, immune response, and cell adhesion, primarily through the uptake of fatty acids." (PMID 39967663, 2025). "Free fatty acids released by tumor cells are extensively taken up by M2 macrophages through extracellular vesicles and CD36, promoting their immunosuppressive phenotype." (PMID 40718481, 2025).
tumor (continued). "CD36-mediated uptake of FAs is also closely associated with the induction of epithelial-mesenchymal transition (EMT), which is a key process in tumor tissue that confers both chemotherapy resistance and invasiveness." (PMID 41421797, 2025). "Results showed that KPC tumor-induced increase in the mRNA levels of Fbxo32, Trim63, Map1lc3b, Cd36, Acox3, and spliced-Xbp1 (sXbp1) in skeletal muscle were significantly reduced by treatment of mice with 4μ8C." (PMID 40655023, 2025). "CD36, for example, facilitates metabolic signaling in cancer cells and TAMs, promoting tumor growth." (PMID 40358184, 2025). "An integrated analysis of combined samples of GTEx and TCGA datasets showed significantly differential expression of CD36 in various cancers when compared to normal and tumor samples." (PMID 41550652, 2025). "FA uptake in TAMs is mainly conducted by the over-expression of CD36 and FABPs, TAMs uptake the tumor cell-derived FAs via CD36, especially monounsaturated long-chain FAs." (PMID 40709184, 2025). "There was also a constructive relation found between CD36 expression and clinical attributes, including Stages, Grades, Metastasis (M), Nodes (N), and Tumor (T) in various cancers." (PMID 41550652, 2025). "Cancer cells increase the expression of fatty acid transport proteins, such as CD36, to efficiently absorb free fatty acids (FFAs) from the tumor microenvironment." (PMID 40391753, 2025). "This platform targets CD36 on tumor-resident immune cells (TRICs), inhibiting lipid uptake and alleviating their immunosuppressive phenotype, thereby promoting CD8+ T cell infiltration." (PMID 40137165, 2025). "In obese TNBC patients, FABP4 upregulates ANGPTL4 and CD36, enhancing tumor angiogenesis and chemoresistance." (PMID 40717587, 2025). "In the tumor microenvironment of melanoma, for instance, cholesterol promotes the expression of CD36 on tumor-infiltrating CD8+ T cells, leading to increased fatty acid uptake, lipid peroxidation, and ferroptosis." (PMID 40659633, 2025). "CD36 is selectively up-regulated in tumor Tregs, regulates mitochondrial function through PPARβ signaling, and adapts Tregs to the lactate-rich TME, suppressing tumor immunity." (PMID 40696413, 2025). "These lipids are taken up by tumor cells via transport proteins such as CD36, providing energy and membrane synthesis materials for tumor cells." (PMID 40718481, 2025). "Blocking CD36 can reduce regulatory T cells and increase cytotoxic T cells in the tumor, inhibiting tumor growth." (PMID 40733687, 2025). "It has been demonstrated that cholesterol orchestrates metabolic reprogramming in the tumor microenvironment (TME) by means of upregulating CD36 expression." (PMID 40430847, 2025). "Due to the high expression of SLC7A11, tumor cells outcompete T cells for cystine uptake, a mechanism that promotes CD36-mediated CD8 + T cells." (PMID 41326356, 2025). "In tumor cells, high expression of CD36 promotes fatty acid uptake and metabolic reprogramming, which correlates with malignant tumor biological behaviors." (PMID 40640171, 2025). "Elevated CD36 expression is closely associated with hypoxic signaling and HIF-2α activation in tumor tissues, promoting lipid-droplet accumulation through DGAT1-dependent triglyceride synthesis." (PMID 41451091, 2025). "The UPS regulates key FA transporters, such as CD36 and fatty acid-binding proteins (FABPs), modulating lipid metabolism and tumor progression." (PMID 40370434, 2025). "Simultaneously, QR suppresses CD36 expression epigenetically,reducing fatty acid uptake, inhibiting tumor proliferation, and downregulatingCD47 expression." (PMID 39871538, 2025). "An efferocytosis-based prognostic model, EFFscore, developed based on ADAM9, P2RY6, and CD36, can effectively assess the tumor phenotype of PDAC patients." (PMID 41383622, 2025).
tumor (continued). "CD36 also supports intertumoral Treg survival via PPAR-β–mediated mitochondrial fitness; deletion of CD36 in Tregs boosts anti-tumor immunity, particularly when combined with ICBs." (PMID 41550652, 2025). "CD36 facilitates fatty acid uptake in tumor-infiltrating CD8 + T cells within the TME, inducing lipid peroxidation and ferroptosis, which leads to reduced cytotoxic cytokine production and compromised antitumor activity." (PMID 41326356, 2025). "During tumor-associated macrophage (TAM) polarization toward the M2-like phenotype (protumoral), peroxisome proliferator-activated receptor-γ (PPARγ) and CD36 are upregulated, and FA uptake and oxidation are promoted." (PMID 39402211, 2025). "By overexpressing fatty acid transport proteins such as CD36, cancer cells actively absorb free fatty acids (FFAs) from the tumor microenvironment, providing an additional exogenous lipid reservoir." (PMID 40391753, 2025). "Palmitic acid or fat-rich diets can specifically enhance the metastatic potential of cancer cells expressing high levels of CD36, suggesting the role of dietary lipid components and CD36 in the tumor metastasis process." (PMID 40137165, 2025). "Our findings highlight the potential of CD36 in prognosis, tumor microenvironment, and therapeutic sensitivity, while experimental validation is required to prove therapeutic relevance in cancer therapy and immunotherapy." (PMID 41550652, 2025). "By regulating lipid metabolism, CD36 accelerates tumor growth and metastasis, mediates chemo- and radio-resistance, and modulates the tumor immune microenvironment." (PMID 40640171, 2025). "Both in vitro and in vivo experiments have confirmed that CD36 regulates tumor growth, metastasis, and drug resistance through multiple molecular mechanisms." (PMID 41041664, 2025). "Further, the uptake of arachidonic acid and oxidized lipids by the scavenger receptor CD36 in tumor-infiltrating CD8+ T cells can induce lipid peroxidation and ferroptosis, leading to reduced cytotoxic cytokine production and impairing anti-tumor function." (PMID 39851538, 2025). "CD36 expression was significantly correlated with tumor stage, mode of invasion, differentiation, and recurrence of OSCC cells." (PMID 41465497, 2025). "Studies have shown that tumor cells utilize CD36 on their cell surface to uptake fatty acids, and CD36 is overexpressed in HCC cells." (PMID 40370433, 2025). "CD36 (type 2 cell surface scavenger receptor), which is responsible for lipid transportation, was found to be highly expressed on tumor infiltrating CD8+ T cells, promoting intratumoral CD8+ T-cell dysfunction." (PMID 40872545, 2025). "Key genes, including CD36, FABP4, PLIN1, PLIN4, SCD5, and ACSLs, were consistently downregulated in tumor tissues, with further reductions observed in KRAS-mutated samples." (PMID 40860798, 2025). "The study revealed that CD36−/− CD8+ T cells enhanced tumor regression and restored cytotoxic T lymphocytes (CTL) effector function and cytokine production." (PMID 40872545, 2025). "The functional diversity and versatility of CD36 can mediate epithelial-mesenchymal transition in a wide range of tumour cells, promoting tumour progression and metastasis." (PMID 40565598, 2025). "Our present study revealed that CD36 is essential for the engulfment of B-cell-derived MHC-II molecules by MDSCs via direct cell‒cell contact in tumor models." (PMID 40959278, 2025). "Mechanistically, CD36 exerts its tumor‐suppressive effect by regulating the expression and activity of CAV1 via PPARγ, which increases intracellular lipid peroxidation and promotes ferroptosis in TNBC cells." (PMID 41267927, 2025). "Although this study confirms the critical role of CD36 in ferroptosis induction and tumor suppression in TNBC, several important limitations warrant acknowledgment." (PMID 41267927, 2025).
tumor (continued). "After uptake of fatty acids, CD36 preferentially transports them to metastasis-associated macrophages (MAMs) in the TME to enhance their metabolic activity and thus play a tumor-promoting role." (PMID 40696413, 2025). "Western blot analyses further confirmed increased levels of CD36 and Serpine1, suggesting enhanced platelet activation and potential involvement in lipid metabolic crosstalk during tumor progression." (PMID 40990541, 2025). "In-vivo murine tumor models described CD36's potential to respond to immunotherapy in various cohorts." (PMID 41550652, 2025). "This restored TSP-1’s anti-tumor effects: binding tumor CD36 to induce apoptosis, inhibited angiogenesis, and promoted macrophage infiltration, significantly suppressing tumor growth and metastasis without observed toxicity." (PMID 40801564, 2025). "Specifically, TAMs take up tumor-derived monounsaturated long-chain FA via CD36, promoting their polarization toward the M2 phenotype." (PMID 41432903, 2025). "Concurrently, tumor cells enhance PUFA uptake via transport molecules like CD36, which is influenced by the lipid composition available in the TME." (PMID 40285867, 2025). "During malignant transformation, cancer cells undergo lipidomic remodeling and express the transport protein CD36, a fatty acid translocase that enables tumor cells to uptake fatty acids from adjacent adipocytes." (PMID 41228384, 2025). "Studies have shown that CD36 on the surface of CD8 + T cells promotes the uptake of oxidized lipids from the tumor microenvironment, which triggers a signaling cascade leading to T-cell dysfunction and an exhausted phenotype." (PMID 41212437, 2025). "CD36, a fatty acid translocase, enhances lipid uptake in tumor-infiltrating CD8+ T cells, which has the potential to drive excessive lipid peroxidation and ferroptosis." (PMID 40430847, 2025). "For relapse, significant prognostic factors included the T factor (p = 0.0014), N factor (p = 0.017), tumor stage (p = 0.016), mode of invasion (p < 0.0001), and CD36 expression (p = 0.0008)." (PMID 41465497, 2025). "Our findings identify CD36 as a novel tumor suppressor in TNBC that acts by promoting ferroptosis, highlighting its potential as both a prognostic biomarker and a therapeutic target." (PMID 41267927, 2025). "Experimental studies have shown that pharmacological inhibition or genetic silencing of FASN, SCD1, or CD36 can impair lipid metabolic flux, disrupt membrane architecture, and suppress tumor growth and chemoresistance." (PMID 41350297, 2025). "Tumor-associated macrophages (TAM) tend to absorb a large amount of oxidative lipids released by tumor cells in ccRCC through scavenger receptors (such as CD36)." (PMID 41555916, 2025). "In this study, CTT activated splenic B cells, which inhibited tumor metastasis, promoted the maturation of MDSCs through CD36-dependent MHC-II transfer and subsequently stimulated the Th1-dominant T-cell immune response." (PMID 40959278, 2025). "CD36 has been shown to play a significant role in various pro-tumor functions, including the regulation of proliferation, metastasis, resistance to chemotherapy or radiotherapy, and angiogenesis." (PMID 41465497, 2025). "Blocking CD36-mediated lipid uptake on cytotoxic CD38+ T-cells or Tregs enhances anti-tumor immune response(s)." (PMID 40563926, 2025). "Increased CD36 expression on tumor-infiltrating CD8+ T cells, compared to normal tissue T cells, is driven by high cholesterol levels in the tumor microenvironment and is associated with tumor progression and poor survival." (PMID 40270603, 2025). "Elevated expression of CD36—a key fatty acid transporter—intensifies tumor cell reliance on the lipid supply from TAMs, and targeting CD36 disrupts fatty acid transfer while inhibiting metabolic adaptation in metastatic tumor cells." (PMID 40904700, 2025).
tumor (continued). "This process is mainly mediated by upregulated CD36 in tumor-infiltrating macrophages, which play a pro-tumorigenic role after phagocytosis of lipids in the tumor cells via a CD36-dependent mechanism." (PMID 40034694, 2025). "Other studies have demonstrated the role of FA metabolism in promoting tumor-associated macrophages (TAMs) in the TME: TAMs internalize FA primarily through key lipid transporters, including FA translocase (CD36)." (PMID 41432903, 2025). "Thbs1 is a ligand for CD36 and CD47 receptors and it is implicated in angiogenesis, tumor growth and thromboembolism." (PMID 40841769, 2025). "CD36 demonstrated a significant decrease (0.24) during the transition from normal to tumor, with an even more pronounced decrease in the metastatic stage (FC_MvsN = 0.15)." (PMID 40565366, 2025). "Functional studies in TNBC cells further revealed that CD36 inhibits proliferation, migration, and invasion, aligning with its proposed tumor‐suppressive role in this subtype." (PMID 41267927, 2025). "Prolonged exposure to tumor‐derived lipids, particularly through the CD36‐mediated uptake of oxidized LDL, sustains TAMs in an immunosuppressive state." (PMID 40904700, 2025). "Emerging evidence elaborates the immune-metabolic crosstalk driven by CD36 in the tumor microenvironment (TME)." (PMID 41550652, 2025). "The colocalization of CD36 with immunosuppressive markers in melanoma cancer cells differed in SLN (−) and SLN (+), which differentiate the direct role of the tumor in generating a CD36-mediated effect in the neighborhood cells." (PMID 39062552, 2024). "Whereas tumor‐associated macrophage (TAM) family members, integrins (e.g., αVβ3 and αVβ5) and CD36 are phagocytic receptors that indirectly recognize PtdSer on ACs by bridging molecules, while CD36 binds directly to oxidized PtdSer." (PMID 39188510, 2024). "Blocking CD36 or inhibiting ferroptosis in CD8 T cells effectively restores its anti-tumor activity." (PMID 39192972, 2024). "The authors demonstrated that CD36 siRNA decreased cell invasion by over 65% in the MDA-MB-231 cell line, indicating that CD36 plays a role in tumor metastasis." (PMID 38370376, 2024). "The upregulation of TLR3 (3.79×) and CD36 (2.73×), two general tumor markers, and SERPINEB9 (11.37×), FNDC1 (7.58×), and TACR2 (8.84×), three factors of tumorigenesis, confirms the wider pathological significance of this bacterium." (PMID 38787238, 2024). "Although not required by the study protocol, paired pre- and on-study tumor tissue samples were voluntarily obtained from 7 patients and were analyzed by IHC for expression of CD36, CD47 and TSP-1." (PMID 38218979, 2024). "Uptake of these tumor-derived vesicles correlated with CD36 expression and was significantly decreased in CD36 KO MAMs." (PMID 39742252, 2024). "Studies have revealed that tumor-infiltrated Treg cells significantly up-regulate the expression of multiple fatty acid-binding proteins and CD36, which are responsible for the uptake of long-chain fatty acids and oxidized low-density lipoproteins." (PMID 39596288, 2024). "CD36 levels increase in tumor-infiltrating CD8 + T cells, which induces the uptake of FAs, particularly arachidonic acid (AA), to increase FAO and ferroptosis." (PMID 38302980, 2024). "To analyze the tissue expression of CD36 and its association with other LN resident cells, we analyzed the tumor-involved LN (SLN+) and tumor-uninvolved LN (SLN−) and compared them to the normal one using a spatial MxIF analysis." (PMID 39062552, 2024). "In a recent study, CD36 expression decreased cytokine release and inhibited the anti-tumor activity of B16 tumor-infiltrating CD8+ T cells owing to CD36-mediated lipid peroxidation and ferroptosis." (PMID 38915413, 2024). "Further investigations revealed that cholesterol in the TME induces CD36 overexpression in tumor-infiltrating CD8+ T cells." (PMID 39614322, 2024).